AXL (AXL receptor tyrosine kinase)
Diseases named in the same sentence as AXL in open-access papers (continued):
Sharing a sentence is not in itself a finding about the gene and the disease.
breast carcinoma (continued). "AXL’s involvement in the EMT process is not limited to its function as a downstream effector, i.e., an effector activated only when the transition to a mesenchymal phenotype has to be promoted; in breast cancer stem cells (BCSCs), indeed, it also exerts a direct influence in this phenomenon." (PMID 33182542, 2020). "Furthermore, we found that the TNBC cell lines (MDA-MB-231 and Hs578T) which endogenously express KISS1R also robustly express AXL, but the ERα-positive breast cancer cells (T47D and MCF7), that barely express KISS1R, do not express AXL." (PMID 28422142, 2017). "In addition, a decrease in the expression of AXL, a novel receptor tyrosine kinase known to be an essential EMT-induced regulator of breast cancer and regulated by MZF-1, was also observed, and the decrease can be reversed by rescuing MZF-1 expression with protease inhibitor." (PMID 27542222, 2016). "However, no data are available on AXL expression in CTCs from patients with breast cancer." (PMID 38132919, 2023). "In addition, AXL-negative MCF-7 breast cancer cells were selected as control cells in our study." (PMID 31998790, 2020). "Moreover, the AXL-negative breast cancer cell line, MCF-7, was selected as the control." (PMID 31998790, 2020). "Here, we provide experimental evidence that the miR-34a–AXL axis is critical for the regulation of VM formation via the regulation of EMT, and it may serve as a potential therapeutic target to overcome the limitations of anti-angiogenic therapy in breast cancer." (PMID 33374832, 2020). "However, a ligand-independent mechanism was also demonstrated for AXL activation either by reactive oxygen species, by homodimerization upon AXL overexpression, or by heterodimerization with EGFR (epidermal growth factor receptor) as was shown in a breast cancer model." (PMID 28118606, 2017). "However, the successful approval of TKIs to treat ROS1-, RET-, NTRK1-, PDGFR-α, and AXL-rearranged NSCLC is vitally important as it sets the example for approval of TKIs to treat the same RTK-rearranged common epithelial tumors such as colon, gastric, and breast cancers." (PMID 24744988, 2014). "AXL is highly expressed in TNBC cells and can promote the stemness of breast cancer, but the mechanism is still not clear enough and needs further exploration." (PMID 36042208, 2022). "Emerging evidence suggests a functional crosstalk between the TGFβ and AXL signaling pathways in hepatocellular carcinoma (HCC) and breast cancer, while their role in CRC has never been addressed before." (PMID 33570712, 2021). "Expression of AXL was high only in the two TNBC cell lines, MDA-MB-231 and Hs578T, and not in the other two breast cancer cell lines (MCF-7 and T47D) or in the normal human breast epithelial cell line." (PMID 29097911, 2017). "Similarly, in an SNAI1-induced EMT model, EMT markedly upregulated representative YAP target genes, including AXL, CTGF, CYR61, and GLI2, in human breast carcinoma cells in media with or without serum." (PMID 40940864, 2025). "If other TAM family members are shown to be involved in breast cancer progression, it could indicate that more broad-spectrum TAM inhibitors as opposed to more highly selective AXL inhibitors may be more effective in breast cancer treatment." (PMID 32148495, 2020). "However, AXL silencing did not have any effect on the FGF2, VEGF-A, FGFR1, VEGFR1, and VEGFR2 expression of MDA-MB-231 breast cancer cells (data not shown), suggesting that AXL-mediated VM formation may be independent of the VEGF/VEGFR and FGF/FGFR axis." (PMID 33374832, 2020).
ZIKV infection (68 papers, 2016 to 2025). "In placental cell cultures and chorionic villi explants, susceptibility to ZIKV infection is mediated via AXL, TYRO3, and TIM1." (PMID 38137537, 2023). "We demonstrated the important roles of AXL and TIM-1 in ZIKV infection of trophoblast cells by gene knockout and overexpression of AXL or TIM-1 in EVTTS enhanced susceptibility to ZIKV infection." (PMID 37684223, 2023). "In the placenta, increased AXL has been implicated in ZIKV infection and inflammatory-associated obstetrics complications, suggesting its essential role in disease development." (PMID 36429055, 2022). "It is important to note that neural crest cells (NCCs) are susceptible to ZIKV infection since they express AXL." (PMID 35736984, 2022). "The inhibition of AXL during a ZIKV infection in Sertoli cells causes: (i) the inactivation of STAT1, (ii) the reduction of SOCS-1, and (iii) an interferon-induced antiviral gene (ISG) expression that decreases the viral replication." (PMID 36557673, 2022). "Cystatin B (CSTB), the receptor for advanced glycation end products (RAGE), and tyrosine-protein kinase receptor UFO (AXL) have been implicated in ZIKV infection and inflammation." (PMID 36429055, 2022). "A similar conclusion was reached for mice in vivo, because brains, eyes and testes retained their susceptibility to ZIKV infection in AXL-deficient mice." (PMID 34578404, 2021). "Additionaly, using an in vitro primary human brain vascular pericyte model, we show that brain pericytes are indeed susceptible to ZIKV and ZIKV infection is dependent on AXL." (PMID 32357162, 2020). "ZIKV infection augments the number of AXL in fetal mouse brain tissues suggesting a clear association between ZIKV infection and the virus mode of access to a developing fetal brain." (PMID 29276699, 2017). "We next investigated a distinct mechanism by which the H83R mutation may govern AXL dependency for ZIKV infection of SNB-19 cells." (PMID 40062839, 2025). "Furthermore, AXL is overexpressed in multiple developing human brain cells (including astrocytes, microglia, and radial glial cells), these cells are highly susceptible to ZIKV infection." (PMID 33954117, 2021). "Here, we report that AXL is an important host factor for ZIKV infection in glioblastoma cells as identified by a genome-wide CRISPR/Cas9 screen." (PMID 40062839, 2025). "Lentiviral vectors expressing WT AXL, a kinase-dead mutant of AXL (AXL N90G and AXL-KD), Tyro, and Mer were delivered into the AXL KO cells individually, followed by ZIKV infection." (PMID 40062839, 2025). "We consider it unlikely that this was due to residual levels of AXL, as ZIKV infection still occurs in cell clones where both western blots and genomic sequencing clearly demonstrate a clean KO." (PMID 40062839, 2025). "Although ZIKV infection of AXL KO cells was significantly reduced, a low level of infection was still detectable, suggesting the possibility of selecting and enriching mutant viruses that infect these cells in an alternative AXL-independent manner." (PMID 40062839, 2025). "There is still a low level of ZIKV infection which increases in a dose-dependent manner even in our AXL KO SNB-19 cells." (PMID 40062839, 2025). "In contrast, expression of Tyro or Mer tyrosine kinases did not rescue infection despite similar expression levels, suggesting that AXL is the only TAM family member that can function to mediate ZIKV infection of these glioblastoma cells." (PMID 40062839, 2025). "In this report, we establish an essential role of AXL during ZIKV infection of human glioblastoma cells, a proposed target cell type for potential oncolytic viral therapy (10, 43, –, 47)." (PMID 40062839, 2025). "In line with AXL expression, the retinal cell tropism of ZIKV coincides with the AXL-specific expression pattern in C57BL/6 ZIKV-infected embryos, and the inhibition of AXL expression suppresses ZIKV infection in human microglia and astrocytes." (PMID 38137537, 2023).
ZIKV infection (continued). "The TAM receptors Tyro3 and AXL, candidate receptors for Zika virus infection, are also expressed on moDCs." (PMID 36949942, 2023). "The overexpression of Mertk and AXL, and the downregulation of Tyro-3 suggest that these are receptors that promote ZIKV infection in our culture." (PMID 36989308, 2023). "Studies using neutralizing antibodies or small interfering RNA targeting AXL have significantly reduced ZIKV infection in human skin fibroblasts, proposing AXL as a potential entry receptor for ZIKV." (PMID 38137537, 2023). "We analyzed the expression of Tyro-3, AXL, and Mertk basally and upon ZIKV infection in our hNS1-derived astrocyte cultures." (PMID 36989308, 2023). "The expression levels of AXL and TIM-1 contribute to the susceptibility of hTSC-derived trophoblast cells to ZIKV infection." (PMID 37684223, 2023). "Taken together, these results demonstrated the essential roles of AXL and TIM-1 in the susceptibility of hTSC-derived trophoblast cells to ZIKV infection." (PMID 37684223, 2023). "Significantly attenuated ZIKV infection was found in AXL-/- and TIM-1-/- hTSCs compared to WT hTSCs." (PMID 37684223, 2023). "In human pluripotent stem cells (hPSC)-derived microglia, ZIKV infection induced the differential expression of AXL, TYRO3, MERKT, and TIM." (PMID 38137537, 2023). "Our quantitative proteomics results further validate the involvement of the proteins CSTB and AXL in ZIKV infection of the placenta." (PMID 36429055, 2022). "In this study, we characterized the ZIKV infection, evaluated the antiviral profile, and demonstrated the AXL and TIM-1 expression on the PC3 prostate cell line." (PMID 36557673, 2022). "It is of note that ZIKV infection in primary dermal fibroblast was significantly decreased by RNA inhibitor and neutralizing antibody to AXL." (PMID 35308394, 2022). "The expressions of the AXL and TIM-1 receptors were demonstrated in the PC3 and Vero E6 cells, and thus, they were defined as being susceptible to a ZIKV infection." (PMID 36557673, 2022). "We propose that AXL exerts control over the antiviral response in a ZIKV infection, as when cells are infected at a high MOI (MOI = 3), the receptor expression increases, unlike in TIM-1, so the latter only has a role in virus entry." (PMID 36557673, 2022). "AXL plays a pivotal role in maintaining the immunosuppressive milieu of the testis, enhancing ZIKV infection by negatively regulating antiviral immune response." (PMID 36089062, 2022). "In astrocytes, pre-treatment of the cells with antibodies targeting AXL managed to reduce ZIKV infection." (PMID 35371036, 2022). "It’s indicated that significant activation of the type I interferon pathway occurs until the late stage of ZIKV infection, mainly because virus hijacked the host protein such as AXL to interfere in the activation of IFN signaling pathway." (PMID 36209057, 2022). "The developing human brain cells such as radial glia, astrocytes, endothelial and microglia overexpress AXL protein, and they are especially vulnerable to ZIKV infection." (PMID 35371036, 2022). "Type II IFN (IFNγ) are key inducers of proinflammatory cytokines such as IRF1, IFIT1, CXCL10 and crucially, known cellular receptors for ZIKV infection such as AXL, Tyro3, and DC-SIGN." (PMID 35536870, 2022). "In summary, we demonstrate that Hc-CATH provides prophylactic and therapeutic efficacy against ZIKV infection via downregulation of AXL, as well as inactivating the virion." (PMID 36089062, 2022). "At 24 h post Hc-CATH addition, Hc-CATH also decreased the level of AXL in Vero cells relative to PBS upon ZIKV infection." (PMID 36089062, 2022). "This correlation between AXL expression and ZIKV infection is consistent with previous findings in vitro." (PMID 34272257, 2021). "Among the most well characterized for ZIKV infection is the phosphatidylserine binding TAM family receptor AXL." (PMID 35126336, 2021).
ZIKV infection (continued). "AXL reportedly can play a dual role in ZIKV infection, serving both to facilitate viral entry and also, via it’s kinase activity, to regulate viral replication in the cell." (PMID 35126336, 2021). "It is reported that AXL is required for efficient ZIKV infection in Sertoli cells, brain glial cells, astrocytes, and endothelial cells." (PMID 35126336, 2021). "Future studies should leverage scRNAseq data to mark multiple viral entry receptors with RNAscope to further understand how AXL interacts with other entry receptors in aRGC ZIKV infection." (PMID 34272257, 2021). "As the first barrier of innate immunity, multiple cells (including immature dendritic cells and epidermal keratinocytes) are permissive to ZIKV infection, and these cells highly expresses AXL." (PMID 33954117, 2021). "Accordingly, this aligns with the high concurrence of microcephaly and ocular abnormalities, whilst the unique expression of AXL within radial glial populations offers an explanation to the severe neurodevelopmental prenatal phenotype upon ZIKV infection." (PMID 33499699, 2021). "The results indicate that one class of aRGCs preferentially express the putative ZIKV entry receptor AXL and that these cells are more vulnerable to ZIKV infection than other aRGC subtypes with low AXL expression." (PMID 34272257, 2021). "Nevertheless, the high correlation between Prc1 expression, AXL expression, and ZIKV infection make AXL an interesting group 1 candidate marker gene." (PMID 34272257, 2021). "To further validate our findings, we assessed cell viability using intracellular ATP measurements in fcMSCs that were treated with anti-AXL antibody for 1 h prior to ZIKV infection." (PMID 32941515, 2020). "These putative receptors include Cluster of Differentiation 209 (CD209), Tyrosine-protein kinase receptor Tyro3, and AXL, where overexpression of these receptors in ZIKV-impervious HEK293T cells rendered the cells susceptible to ZIKV infection." (PMID 31959174, 2020). "In particular, the role of AXL in ZIKV infection has been extensively investigated due to its crucial role in dengue virus infection." (PMID 31959174, 2020). "Next, to understand the functional role of AXL in ZIKV infection, we examined the effect of blocking of AXL and growth arrest specific gene-6 (GAS6), ligand for AXL, on ZIKV replication in HBVP." (PMID 32357162, 2020). "Several reports have revealed that SCs, which constitute the BTB, are highly susceptible to ZIKV infection, likely because they express high levels of AXL, a host molecule reported to be a possible attachment receptor or key factor promoting ZIKV infection." (PMID 32302362, 2020). "AXL is expressed in astrocytes and microglia in the human brain development and mediates ZIKV infection of glial cells." (PMID 31866959, 2019). "Both AXL and its ligand Gas6 are essential for ZIKV infection and blocking either one of them would inhibit the infection." (PMID 31824472, 2019). "Nevertheless, the role of AXL in ZIKV infection is still controversial as contradictory findings were reported." (PMID 31824472, 2019). "We reported that inhibition of AXL caused a decrease in ZIKV infection and IFN-β secretion, although AXL is reported to antagonize type 1 IFN signaling to promote ZIKV infection instead of facilitating viral entry in astrocytes." (PMID 30735502, 2019). "The TAM receptor AXL, through soluble intermediates growth arrest-specific 6 (Gas6) was recently shown to support ZIKV infection of human foreskin fibroblast, glial cells, neural stem cells, and foetal endothelial cells." (PMID 30898036, 2019). "Noteworthily, besides serving as an important entry factor for ZIKV infection, AXL and its ligand Gas6 also play an essential role in diverse types of cancer, including GBM which originates from glial cells." (PMID 31824472, 2019). "A recent study further suggests that AXL promotes ZIKV infection in astrocytes by antagonizing type I interferon signalling, rather than promoting ZIKV entry." (PMID 30898036, 2019).
ZIKV infection (continued). "The virus has been shown to utilize the receptor tyrosine kinase AXL and its ligand Gas6 for viral entry, albeit contradictory findings on the role of the receptor in ZIKV infection were reported." (PMID 31824472, 2019). "R448, as well as cabozantinib, an inhibitor of AXL phosphorylation, that are currently in clinical trials for anticancer activities, significantly impairs ZIKV infection of human endothelial cells in a dose-dependent manner by affecting a post-binding step." (PMID 30149598, 2018). "Gain- and loss-of-function tests revealed that AXL is required for ZIKV entry at a post-binding step, and small-molecule inhibitors of the AXL kinase significantly reduced ZIKV infection of hECs." (PMID 29724036, 2018). "In the P7 mouse retinae, the AXL-specific expression pattern was coincident with the retinal cell tropism of ZIKV infection." (PMID 29476066, 2018). "AXL is expressed at high levels in retinal progenitor cells suggesting a possible role in ZIKV infection of ocular cells." (PMID 30319635, 2018). "The potential role of AXL to facilitate ZIKV infection of the neonatal brain was explored by determining, at a single cell level, RNA expression profiles in the developing human cerebral cortex." (PMID 30319635, 2018). "More recently, it has been proposed that AXL promotes ZIKV infection of human astrocytes by antagonizing the IFN response." (PMID 30453621, 2018). "In our study, the AXL expression pattern in the retinae of P7 mice is coincident with the retinal cell tropism of ZIKV infection, which is in line with Nowakowski’s study." (PMID 29476066, 2018). "We next determined if expressing the various PS receptors in SNB-19 AXL KO cells could restore ZIKV infection." (PMID 40062839, 2025). "From the many studies investigating the potential role of AXL in ZIKV infection, it is clear that the AXL requirement is model dependent, as even studies using definitive ablation methods such as gene knockout produced different results in distinct infection models (6, 9, 20, –, 38)." (PMID 40062839, 2025). "Thus, PBMC from SIV-infected PTM have similar/greater levels of ZIKV cellular targets in comparison to naïve PTM and these cells express similar levels of surface AXL, but they are less vulnerable to ZIKV infection ex vivo." (PMID 40103823, 2025). "Indeed, research suggests that other TAM receptors such as TYRO3 and MER also play a role in ZIKV infection, albeit to a lesser extent than AXL." (PMID 40573410, 2025). "Thus, PBMC from SIV-infected PTM have similar/greater levels of ZIKV cellular targets in comparison to naïve PTM and these cells express similar levels of surface AXL, but are less vulnerable to ZIKV infection ex vivo." (PMID 39229223, 2024). "As expected, overexpression of either AXL or TIM-1 significantly enhanced ZIKV infection in EVTTS." (PMID 37684223, 2023). "On the other hand, AXL promotes ZIKV infection by antagonizing type I IFN signaling." (PMID 36089062, 2022). "Blocking of AXL has been shown to inhibit ZIKV infection in glial cells." (PMID 35371036, 2022). "However, another study reported AXL upregulation in microglia, upon ZIKV infection, in microglia-containing 75 day old cerebral organoids, suggesting that AXL has a role in ZIKV infection." (PMID 35337041, 2022). "AXL could activate the HSP27 and cause an upregulation due to response to impaired inflammation and the tissue damage caused by ZIKV infection." (PMID 36429055, 2022). "AXL is a member of TAM receptors that play an important role in ZIKV infection." (PMID 36089062, 2022). "It has been reported that AXL plays an important role in ZIKV infection." (PMID 36089062, 2022). "Actually, AXL may promote Zika virus infection by antagonizing interferon (IFN) signaling in human astrocytes." (PMID 34873039, 2021). "Here, we investigated the role of AXL in ZIKV infection in primary genital epithelial cells." (PMID 35126336, 2021).